JAK2 (Janus kinase 2)
Diseases named in the same sentence as JAK2 in open-access papers (continued):
Sharing a sentence is not in itself a finding about the gene and the disease.
myeloid neoplasm (69 papers, 2011 to 2026). Proliferation of myeloid cells originating from a primitive stem cell. "The role of mutant JAK2 in hematopoiesis has been studied in mouse models utilizing the knockin (KI) strategy of Jak2VF, the most common JAK2 mutation in CH and myeloid neoplasms." (PMID 39744945, 2025). "Germline predisposition to myeloid neoplasms due to pathogenic or likely pathogenic variants of JAK2 gene are emerging as new disorders; however, in both siblings of Family4, we identified a germline variant currently annotated as VUS: p.G571S." (PMID 39118233, 2024). "The second unique case is another example of a challenging situation where correlation with clinical morphologic features, cytogenetic findings, and molecular findings raises questions on the role of JAK2 mutations on the myeloid neoplasm phenotype." (PMID 36810551, 2023). "The findings in this work provide a potential mechanistic link between CBL/JAK2–mutated myeloid malignancies and activation of RAS signaling via upregulation of RAB27B." (PMID 37317963, 2023). "Subsequent next generation sequencing looking for myeloid neoplasm associated gene mutations showed a concurrent JAK2 V617F mutation with a low allele variance frequency of 8%, causing this case classification to be more challenging." (PMID 36810551, 2023). "This case raises the discussion about the potential impact of different JAK2 mutations and downstream transcription regulators on the clinical and morphologic phenotype of myeloid neoplasms." (PMID 36810551, 2023). "Mutational analyses of 13 genes commonly mutated in myeloid malignancies, including Janus Kinase 2 (JAK2), calreticulin (CALR), thrombopoietin receptor (MPL), and colony‐stimulating factor 3 receptor (CSF3R) was negative on peripheral blood testing." (PMID 35898175, 2022). "Aside from DTA mutations, persons with CH also recurrently carried variants in other genes associated with myeloid neoplasms such as JAK2, SRSF2 and SF3B1." (PMID 36131041, 2022). "Mutations of the JAK2 gene are frequent aberrations in the aging hematopoietic system and in myeloid neoplasms." (PMID 35654819, 2022). "Detection of the JAK2 V617F mutation is part of the diagnostic criteria of myeloid neoplasms in the recent World Health Organization (WHO) classification." (PMID 30056580, 2018). "This review provides an overview of the frequency and the role of the JAK2 haplotypeGGCC_46/1 in the pathogenesis of different myeloid neoplasms and describes the hypothetical mechanisms at the basis of the association with JAK2 gene mutations." (PMID 29641446, 2018). "The presence of genetic abnormalities in genes related to the development of myeloid neoplasms in aging population (e.g., JAK2, DNMT3, TET2, and ASXL1) is associated with increased risk of hematologic malignancies, all-cause mortality, and cardiovascular disease." (PMID 30056580, 2018). "The majority of AHN cases are myeloid neoplasms, including CMML, AML, JAK2 mutated MPN, and MPN/MDS." (PMID 40950415, 2025). "Myeloid neoplasms are known to have chromosomal translocations that regulate PML-RARA, CBFB-MYH11, and RUNX1-RUNX1T1 myeloid transcription factors and JAK2, FLT3, KIT, and RAS, activating driver mutations in signaling pathways." (PMID 38392574, 2024). "Our study indicated that MDS/MPN is characterized by mutations commonly identified in myeloid neoplasms, with TET2 (52%) being the most frequently mutated gene, followed by ASXL1 (38.7%), SRSF2 (34.7%), and JAK2 (19.7%), among others." (PMID 39337700, 2024). "Ren and colleagues have discovered a role of the CBL/JAK2/RAB27B/ZDHHC9 signaling axis in regulating NRAS trafficking to the plasma membrane for activation by palmitoylation in myeloid malignancies." (PMID 37317974, 2023).
myeloid neoplasm (continued). "An additional four CHIP genes (ASXL1, TET2, JAK2, and DDX41) were significantly associated with myeloid neoplasms and are likely driven by somatic alterations." (PMID 36199081, 2022). "In PV and PMF, where the side effects of IFNs are tolerated, treatment using IFNs in combination with JAK2 inhibitors is certainly a possibility for the prevention of disease progression to other myeloid malignancies." (PMID 34778087, 2021). "It was observed that the JAK2 46/1 haplotype is more frequent in patients with chronic inflammatory diseases and with some myeloid neoplasms including MPN." (PMID 34681577, 2021). "BCORL1 and JAK2 gene alterations have been demonstrated in various tumors including myeloid neoplasms." (PMID 34514557, 2021). "For cases lacking typical driver mutations, translocations involving PDGFRA/B, FGFR1 and JAK2, and potentially AML-type alterations, should be investigated in addition to mutations found in myeloid neoplasms (MN) in general." (PMID 34298741, 2021). "Next-generation sequencing (NGS) is used to detect and monitor clonal hematopoiesis, and the spectrum of mutations substantially overlaps with that of myeloid neoplasms with DNMT3A, TET2, ASXL1, and JAK2 being the most frequently mutated." (PMID 32825226, 2020). "Despite a theoretical rationale and profound preclinical proof of HDACi efficacy in myeloid malignancies, all phase II randomized clinical trials have failed, except for the combination of HDACi with JAK2 inhibitor ruxolitinib in MF." (PMID 30304859, 2018). "Evidence for BCL2 inhibition in this setting is limited to anecdotal reports, including a recent case describing prolonged disease control with ruxolitinib plus venetoclax in a BCR::JAK2-rearranged myeloid neoplasm, suggesting potential synergistic activity of JAK2 and BCL2 blockade." (PMID 41530508, 2026). "JAK inhibitors are effective in treating CBL or JAK2 mutated myeloid malignancies, but they are not curative." (PMID 37317963, 2023). "Other alterations that activate JAK2, such as fusions or amplifications, may also confer sensitivity to JAK2 inhibitors on the basis of clinical data in myeloid neoplasms as well as preclinical data." (PMID 36551764, 2022). "It has been reported that an SF3B1 mutation is an early event in myeloid neoplasms, and in MDS/MPN, SF3B1 mutations seem to represent founder mutations followed by secondary hits in genes involved in other signaling pathways, such as JAK2." (PMID 36671709, 2022). "In this context, identifying mutations in MPN driver genes (JAK2, CALR, or MPL) or other myeloid neoplasm-associated genes (ASXL1, EZH2, TET2, IDH1, IDH2, SRSF2, and SF3B1) hints to the clonality of hematopoiesis and allows distinction from reactive conditions." (PMID 34830822, 2021). "Some TK-fusion negative eosinophilia cases test positive for KIT D816V or JAK2 V617F, whereas others have mutations in a range of genes associated with myeloid neoplasms such as TET2, ASXL1, EZH2 or SETBP1." (PMID 30573779, 2019). "JAK2 V617F, a somatic point mutation that leads to constitutive JAK2 phosphorylation and kinase activation, has been incorporated into the WHO classification and diagnostic criteria of myeloid neoplasms." (PMID 22028900, 2011). "The phenotype of myeloid neoplasms may depend on the intensity of signaling on specific downstream targets in the JAK-STAT signaling pathway, which is related to the number of JAK2 V617F copies and the presence of additional gene mutations affecting RNA splicing genes or epigenetic regulators." (PMID 36810551, 2023). "These myeloid malignancies arise due to acquired somatic stem cell lesions affecting calreticulin (CALR), myeloproliferative leukemia virus proto-oncogene (MPL), and the tyrosine kinase Janus kinase 2 (JAK2), usually displaying a valine-to-phenylalanine mutation at 617 (JAK2V617F)." (PMID 36910610, 2023).
myeloid neoplasm (continued). "All patients with concurrent presence of BCR::ABL1 and JAK2 V617F (JAK2 V617Fpos/BCR::ABL1pos) gave written informed consent to be included in the German Registry of Eosinophils, Mast Cells and rare myeloid neoplasms." (PMID 40681596, 2025). "In certain settings, for example in cells with high levels of phospho-JAK2, CARM1 phosphorylation appears to be required for maximal proliferation of myeloid neoplasms." (PMID 38649367, 2024). "We previously reported that protein ubiquitination by CBL and CBL-B controls JAK2 stability and activity that is important for curbing hematopoietic stem and progenitor cell (HSPC) expansion and myeloid malignancies." (PMID 37317963, 2023). "Likewise, venous thromboembolic events represent both initial manifestations of an underlying MPN but may also be associated with a JAK2 V617F mutation without the clinical phenotype of a concomitant myeloid neoplasm." (PMID 35215273, 2022). "Currently, two JAK inhibitors have been approved for myeloid malignancies: Ruxolitinib (JAK1/JAK2 inhibitor) for the treatment of primary and secondary MF, and hydroxyurea resistant PV, and fedratinib (JAK2 inhibitor) for PMF." (PMID 33672930, 2021). "Hence, this work reveals what we believe to be new signaling dynamics that enhance our understanding of compartmentalized RAS signaling, suggesting RAB27B as a therapeutic target to abrogate oncogenic CBL/JAK2 and RAS-driven myeloid malignancies." (PMID 37317963, 2023). "About ten years after its discovery, the possible pathogenic role of the JAK2 haplotypeGGCC_46/1 in MPN patients, as well as in other myeloid malignancies, is not yet understood." (PMID 29641446, 2018). "Hence, we believe that this work uncovered a new signaling dynamic that enhances our understanding of compartmentalized RAS signaling, suggesting that targeting RAB27B may be therapeutically useful in oncogenic CBL/JAK2 and RAS driven myeloid malignancies." (PMID 37317963, 2023). "Previous research from Dr. Wei Tong’s laboratory has shown that ubiquitination of JAK2 by CBL and CBL-B regulates the stability and activity of the JAK2 protein, playing a critical role in curbing HSPC expansion and preventing the development of myeloid malignancies." (PMID 37317974, 2023). "In this study, we examine the efficacy of the USP9X inhibitors WP1130 and G9 on cells expressing wild-type JAK2 or JAK2-V617F, including the ruxolitinib-persistent cells, comparably, to explore the therapeutic potentials of USP9X inhibition against JAK2-V617F-driven myeloid neoplasms." (PMID 32050632, 2020). "The JAK2 V617F is not specific to MPN alone, in which it can be found in less than 5% of patients with AML, MDS, CML and other myeloid malignancies." (PMID 30564475, 2018).
prostate carcinoma (68 papers, 2008 to 2025). A carcinoma that arises from epithelial cells of the prostate gland. "For instance, JAK2 has been associated with tumor mutational burden in prostate cancer, and STAT3 is recognized as a pivotal regulator in inflammatory and tumor signaling networks." (PMID 40978029, 2025). "In prostate cancer, sustained activation of the JAK2/STAT3 pathway is linked to tumor progression and poor patient prognosis." (PMID 40978029, 2025). "SNPs in the JAK2 gene have been associated with cancer risk, such as cervical, gastric, and prostate cancers." (PMID 32973967, 2020). "In a Pten-deficient prostate cancer model, characterized by massive infiltration of immunosuppressive myeloid cells, JAK2 inhibition decreased tumour growth and restored anti-tumour immunity." (PMID 27406745, 2016). "Accordingly, JAK2-mediated local inflammation and oxidative activation may affect the physiological processes of erection and may increase the risk of prostatitis and prostate cancer." (PMID 37407943, 2023). "Emerging studies revealed that PTEN loss in prostate cancer resulted in an immunosuppressive tumor microenvironment through the activation of the Janus kinase 2 (JAK2)–signal transducer and activator of transcription 3 (STAT3) pathway and the subsequent secretion of immunosuppressive chemokines." (PMID 33874915, 2021). "Furthermore the co-cultures of prostate cancer cell lines with either the cells of the innate or adaptive IR was associated with JAK2/STA3 pathway activation." (PMID 30134795, 2018). "Dysregulated IL-6/JAK2 signaling has also been implicated in prostate cancer tumorigenesis." (PMID 21533169, 2011). "This suggests that Osthole inhibits the progression of prostate cancer by targeting the JAK2/STAT3 pathway." (PMID 40978029, 2025). "β-elemonic acid inhibits growth of human castration-resistant prostate cancer cells through the suppression of JAK2/STAT3/MCL-1 signal pathways." (PMID 40830747, 2025). "Additional oncogenic cascades activated by Ang II include PAX2, STAT3, and JAK2 in prostate cancer and RAS/RAF/ERK1/2 in gastric malignancies." (PMID 40722848, 2025). "It has been reported that the atypical activation of the JAK2/STAT3 signaling pathway is an essential basis of prostate cancer." (PMID 39771106, 2024). "Previous studies showed that BaP affected the JAK2/STAT3 pathway by activating AhR to promote prostate cancer progression." (PMID 38410974, 2024). "EA is also known to suppress the growth of prostate cancer cells and trigger the apoptosis of castration-resistant prostate cancer cells by attenuating the JAK2/STAT3/MCL-1 and NF-κB signaling pathways." (PMID 35242040, 2022). "PRL induces PRLR-mediated Jak2-STAT signaling in prostate cancer, and in colon cancer by modulating Notch signaling in a Jak2-STAT3/ERK manner." (PMID 34572912, 2021). "In summary, STING in tumor cells contributes to tumor rejection in prostate cancer cells, but its functions are frequently suppressed in tumor cells in part via JAK2 and STAT3 pathways." (PMID 33790360, 2021). "PRL (endocrine or autocrine), acting via the PRLRLF in vivo, activates the Janus Kinase 2 - Signal Transducer and Activator of Transcription 5 (Jak 2-Stat5a/b) pathway, preventing apoptosis and allowing the survival of prostate cancer cells." (PMID 33179012, 2020). "It was found that STAT3 and JAK2 were phosphorylated in both prostate cancer cell lines as a response to immune attack." (PMID 30134795, 2018). "The in vivo inoculation of DU145 prostate cancer cells with Jak2-STAT5a/b, activated through the expression of prolactin, increased tumor metastasis by 69% in mice." (PMID 30558204, 2018). "Exogenous IL-6 leads to the production and secretion of IL-6 and PEc from prostate cancer cells and tumors, by activating IL-6R and JAK2/STAT3 pathway." (PMID 30134795, 2018). "It was determined that the prostate cancer cells treated with the IIR cells or sensitized lymphocytes presented JAK2 and STAT3 phosphorylation." (PMID 30134795, 2018).
prostate carcinoma (continued). "The DU145 prostate cancer cell line expresses an autocrine IL-6 signaling loop and was recently reported to be sensitive to the effects of a novel small molecule JAK2 inhibitor in vitro and in vivo." (PMID 21533169, 2011). "However, clinical application of PRLR and JAK2/STAT3-targeted therapies for prostate cancer is still limited, partly due to severe side effects like immunosuppression and cytotoxicity." (PMID 40978029, 2025). "Investigating the regulatory mechanisms of PRLR and its downstream JAK2/STAT3 signaling axis in prostate cancer may provide a scientific foundation for the development of novel targeted therapies." (PMID 40978029, 2025). "In our detailed study of the effects of Osthole on prostate cancer, we found that it could suppress tumor growth and metastasis by targeting the JAK2/STAT3 pathway." (PMID 40978029, 2025). "While Osthole might influence other pathways, such as PI3K/AKT, our analysis and experiments emphasize the PRLR - JAK2/STAT3 pathway’s key role in Osthole’s anti - prostate cancer effects." (PMID 40978029, 2025). "We here found that LPHNs induced the growth of prostate cancer cells and that the activation of LPHNs was associated with phosphorylation of JAK2/STAT3, but not Akt or ERK1/2, as well as the increased expression of Bcl-2." (PMID 39000396, 2024). "Additionally, lncRNA LINC00893 regulated the suppressor of SOCS3/JAK2/STAT3 pathway by acting as a ceRNA to bind with miR-3173-5p in patient with prostate cancer." (PMID 37620751, 2023). "Previous studies investigating therapeutic benefits of dehydrocrenatidine have demonstrated that this natural plant compound acts as a specific inhibitor of the JAK2 signaling pathway and that it inhibits the growth of breast and prostate cancer cells by targeting the JAK–STAT pathway." (PMID 35455398, 2022). "Pre-treatment of prostate cancer cells with zerumbone significantly decreased the radiation-induced expression of phosphorylated ATM (ataxia telangiectasia-mutated) and suppressed the expression of JAK2 and STAT3, which are involved in DNA damage repair." (PMID 30781671, 2019). "Jak2-Stat5 signaling inhibitors potently suppress the growth and induce apoptosis of primary prostate cancer cells and castrate-resistant prostate cancer cells, this inhibitory effect was observed in 75% of primary tumors grown ex vivo in organ explant cultures." (PMID 31366128, 2019). "Prior to determine if this effect is associated with the JAK2/STAT3, protein extracts from prostate cancer cells under the influence of IL-6 with and without the treatment of anti-IL-6R antibody were examined for the phosphorylation of JAK2 and STAT3." (PMID 30134795, 2018). "Prostate cancer cells used in this study expressed IL-6 as a response to immune attack that seemed to be associated with the IGF-1Ec upregulation and PEc secretion, through the activation of JAK2/STA3 pathway." (PMID 30134795, 2018). "Thus, targeting the JAK2/STAT3 pathway offers a promising strategy for prostate cancer therapy." (PMID 40978029, 2025). "However, whether Osthole exerts its effects via PRLR and JAK2/STAT3 signaling in prostate cancer remains unclear." (PMID 40978029, 2025). "Additionally, JAK-inhibitor therapy has emerged as a promising therapeutic strategy to combat ARPI resistance and halt mCRPC progression, and a phase II study is now ongoing to evaluate the effect of pacritinib (JAK2 inhibitor) in biochemically recurrent prostate cancer." (PMID 40164700, 2025). "Moreover, it indicates that JAK2 may serve as a vital target regulating the effects of prostate cancer by binding with 6PPDQ." (PMID 39771106, 2024). "In addition, zerumbone selectively inhibited the IL-6/JAK2/STAT3 pathway and blocked the prostate cancer-associated genes- cyclin D1, IL-6, COX2 (cytochrome c oxidase), and ETS Variant 1 (ETV1); thereby inducing cytotoxicity through G0/G1 cell cycle arrest and causing apoptosis." (PMID 30781671, 2019).